CXCR4 (C-X-C motif chemokine receptor 4)
Diseases named in the same sentence as CXCR4 in open-access papers (continued):
Sharing a sentence is not in itself a finding about the gene and the disease.
tumor (continued). "Therefore, targeting the SDF-1/CXCR4 axis has received considerable attention for inhibiting tumor metastasis." (PMID 25775124, 2015). "In RMS, major characteristic of tumour aggressiveness is represented by the PAX3/7-FOXO1 fusion gene, a negative prognostic factor that regulates transcription of several downstream tumour-driving genes, including c-Met, CXCR4, FGFR4, IGFR-1R and PDGFRα kinases." (PMID 26147305, 2015). "A CSC-like subpopulation expressing CXCR-4 was presented at a higher level (5 % comparing to 0.8 %) in the more aggressive cell line (a metastatic stage), and enriched in tumor spheres derived from both primary cell lines and one established cell line SK-RC-17." (PMID 26210994, 2015). "We speculate that tumor cells with high expression of CXCR4 have strong potential for local invasion, and CXCL12 expressed in lymph nodes has a chemotactic effect on their directional migration." (PMID 25866764, 2015). "CXCR4 is the most frequently expressed chemokine receptor on the tumor cells." (PMID 25503960, 2015). "Blimp-1 was another tumor suppressor that was significantly downregulated in CXCR4+ GCB-DLBCL, and this downregulation may also contribute to the prognostic impact of CXCR4 overexpression." (PMID 25704881, 2015). "Another recent report using triple drugs strategy with anti-PD-1 antibody and CXCR4 inhibitor combined with Sorafenib demonstrated the importance of anti-PD-1 in the enhanced immune activation of tumor microenvironment leading to superior control in tumor growth." (PMID 26287667, 2015). "A decline in CXCR4 within the tumour parenchyma due to drugs was also observed after staining with immunoperoxidase, although quantitative analysis showed statistical significance only with the 50 mg/kg dose of 5-FU (45.7 ± 1.5 compared with 55.9 ± 3.5 for the saline control, P = 0.01)." (PMID 26552750, 2015). "In addition, stem cell factor (SCF), the main growth factor of MCs, was mainly expressed around the tumor-associated vessels, and it was proposed that the tumor-derived CXCL12/CXCR4 attracted MCs." (PMID 26377554, 2015). "However, the high tumor/background ratios observed in the mouse xenograft model are at least partly the result of the selectivity of [68Ga]Pentixafor for human CXCR4." (PMID 25736399, 2015). "Consequently, the growth of tumor cells in the bone and in lung metastases was much less effectively inhibited by CXCR4 antibodies than CXCL12-guided and CXCR4-mediated chemotaxis of metastasizing tumor cells in the circulation." (PMID 24390633, 2014). "In addition, SDF-1/CXCR-4 signal axis functions as an essential messenger for “homing” of myeloid-derived cells to the primary tumor and the metastatic site or niche." (PMID 24587996, 2014). "In these studies both tumor cell and microvascular CXCR4 were identified as potential targets." (PMID 25238146, 2014). "In vivo, tumor weight (P=0.041), lymph node metastasis (P=0.002), the number of pulmonary nodules (P=0.012), the expression of CXCR4 in tumor tissues (P=0.048) and that of SDF-1α in adjacent tissues (P=0.026) were significantly different between the FK506-treated and the NS group." (PMID 24912495, 2014). "Ourimmunostaining approach allowed for the discrimination betweenCXCL12, CXCR4, and CXCR7 expression levelswithin adenocarcinoma, tumor-associated fibroblasts, endothelium, and normal ducts and revealed a pronounced decrease in chemokine within the malignant ductal cell." (PMID 24594697, 2014). "CXCR4 blockade by AMD3100 decreases tumor growth in preclinical GBM models." (PMID 24904289, 2014). "Indeed, these roles are still observed in the adult, as SDF-1/CXCR4 signaling plays a role in adult neurogenesis as well as generating tumor vasculature." (PMID 25191225, 2014). "Furthermore, the CXCR4-positive cancer cells were able to migrate towards higher levels of SDF-1, which was associated with greater invasiveness of the tumor and formation of distant metastases." (PMID 24416254, 2014).
tumor (continued). "Immunohistochemical methods were used to detect the expression of CXCR4 within tumor tissues." (PMID 24932250, 2014). "The direct effect of CXCL12/CXCR4 in tumor metastasis is that CXCL12 increases CXCR4-mediated motility, and the cell surface expression of integrins is mediated by the phosphorylation of extracellular signal regulated kinase (ERK) and downstream activation of the IKKαβ/NFκβ/RELA signaling." (PMID 24944647, 2014). "The scavenging role of CXCR7 on SDF-1 may moderate CXCR4 signalling with high levels of expression of CXCR7 observed on many tumour cell lines and human primary tumour samples." (PMID 24583601, 2014). "In prostate cancer, CXCR4 expression has been shown to increase tumor invasion and metastasis." (PMID 25254213, 2014). "Moreover, the up-regulation of SDF-1/CXCR4 expression is a known mechanism used by some tumour cells that contributes to chemotherapy resistance." (PMID 25162584, 2014). "As such targeting of CXCR4 expression on BMICs may be a potential option for limiting BM formation in some cancers, with a focus on expression modulation as studies have shown antagonism of CXCR4 may enhance a tumor cell’s metastatic ability." (PMID 24857921, 2014). "The tumor-derived exosomes induced the tumor cell to highly express CXCR4 and MMP-9." (PMID 24765179, 2014). "Notably, most CXCL12-positive cells also express CXCR4 strongly suggesting an autocrine/paracrine regulation of tumor cell proliferation." (PMID 25484899, 2014). "Increased CXCL12/CXCR4 signaling has been reported after withdrawal of chemotherapy and shown to promote bone marrow derived endothelial progenitor cell mobilization and subsequent tumor homing, leading to an angiogenic rebound and regrowth of tumors." (PMID 25084358, 2014). "In addition to the staining of tumor cells, CXCR4 staining was observed in inflammatory cells and some parts of nonmalignant tissue adjacent to tumor cells." (PMID 24659999, 2014). "In CLL and other B cell malignancies ibrutinib inhibits SDF1/CXCR4-induced tumor cell migration." (PMID 25294819, 2014). "Differential downregulation of CXCR4 in tumor biopsy and its silencing in CC cell lines prompted us to ask whether autocrine and paracrine SDF-1α differentially regulate the CXCR4 signaling in tumor microenvironment." (PMID 25114911, 2014). "It has been shown that CXCR4 is expressed in many tumor cells and those CXCR4-expressing tumors may show an organ-specific migration to the CXCL12-producing tissues/organs." (PMID 24659999, 2014). "Furthermore, inhibiting CXCR4 in tumor cells has the potential to induce growth arrest or apoptosis and to prevent invasion and metastasis." (PMID 24475985, 2014). "A potential role for CXCR4 in driving OvCa metastasis is further supported by the finding that treatment of xenografted ES-2 cells with a CXCR4 antagonist reduced peritoneal dissemination of the tumor cells." (PMID 24587343, 2014). "Hypoxia, vascular endothelial growth factor (VEGF), transcription factor nuclear factor-κB (NF-κB) and estrogen have been shown to upregulate CXCR4 expression in the tumor microenvironment, leading to cancer cell proliferation, resistance to apoptosis and local invasion." (PMID 24475985, 2014). "The authors concluded that because the reconstituted mice had increased tumor growth in bone compared to control mice that disruption in CXCR4 may increase osteoclastogenesis leading to increased resorption and tumor burden." (PMID 25054153, 2014). "Indeed, we have found a strong correlation between CXCR4 expression and tumor grade (p-value = 0.000085, ρ = 0.4201 at the 95% confidence interval [0.2235; 0.5839])." (PMID 24906407, 2014). "However, inhibition of VEGF was demonstrated to be less efficient than inhibition of the SDF-1/CXCR-4 interactions in abrogating tumor reperfusion and regrowth post-RT." (PMID 24478982, 2014).
tumor (continued). "However, in one instance, with PyV MT tumor cells treated with anti-CXCR4 antibody, there was a significant drop in % invasion towards bone lysate." (PMID 24674692, 2014). "CXCR4 is found on osteoclast precursors and regulates hematopoietic and tumor cell homing to bone." (PMID 25054153, 2014). "In particular, CXCR4/SDF1 system plays a pivotal role in EPCs tumor homing." (PMID 25003596, 2014). "CXCL12/CXCR4 signaling plays an important and unique role in the regulation of stem/progenitor cell trafficking, inflammation, embryo/organogenesis, tissue/organ regeneration, and tumor progression, angiogenesis, metastasis, and survival." (PMID 25216273, 2014). "MiR-146a has a growing list of presumed targets including, TRAF6, IRAK1, CXCR4, NF-κB, which may contribute to inflammation and tumor development." (PMID 25490205, 2014). "CXCL12 (SDF-1) and CXCL13 (BLC) and their respective receptors CXCR4 and CXCR5 have been implicated in tumor growth, metastasis, and are critical for the regulation of the tumor microenvironment in multiple cancer sub-types as a component of the tumor “Immunome”." (PMID 24795716, 2014). "A two-sided Pearson correlation was performed to seek whether a correlation exists between CXCR4 expression and the tumor grades." (PMID 24906407, 2014). "In addition, the growth and invasiveness of an implanted tumor, the expression of CXCR4 in tumor tissues and the expression of SDF-1α in the adjacent tissues to the HCC ones, were examined in vivo, in August Copenhagen Irish rats." (PMID 24912495, 2014). "When CXCR4 expression levels on tumour tissues were measured similar results were observed." (PMID 24981311, 2014). "Although the SDF-1/CXCR4 system mainly functions as a chemotactic factor in cancer cells to seed metastatic sites, recent studies demonstrated that this system also regulates tumor growth, cancer cell-tumor microenvironment interaction and angiogenesis." (PMID 25536052, 2014). "In conclusion, FK506 promotes the proliferation of MH3924A cells, increases the expression of CXCR4 in tumor tissues and that of SDF-1α in adjacent tissues to the HCC ones, enhances the invasiveness of MH3924A cells and significantly intensifies a number of pathological features." (PMID 24912495, 2014). "Recent reports suggest that CXCR4 also plays a decisive role in tumor growth and metastasis." (PMID 24658065, 2014). "In addition, CXCR4 tumor positive cells are characterized by high self-renewal abilities, tumor initiation and resistance to treatment." (PMID 24728301, 2014). "CXCL12 exerts also pro-angiogenic activity, recruiting CXCR4-positive, circulating bone marrow-derived cells and promoting tumor vasculature recovery after irradiation, as a consequence of treatment-induced hypoxia and HIF-1α activation, which results in increased CXCL12 expression." (PMID 24904289, 2014). "Recently it has been shown that tumor cells with high levels of CXCR4 expression orientation migrate to organ sites with high levels of CXCL12/SDF-1 secretion, which suggests that this molecular pair plays a key role in chemotaxis and homing of metastatic cells." (PMID 24941119, 2014). "CXCR4 is the most commonly detected chemokine receptor in tumor cells." (PMID 24966464, 2014). "An interplay exists between CSCs, differentiated GBM cells, and the microenvironment, mainly through secreted chemokines (e.g., CXCL12) causing recruitment of fibroblasts, endothelial, mesenchymal and inflammatory cells to the tumor, via specific receptors such as CXCR4." (PMID 24904289, 2014). "Increased metastatic abilities of tumor cells in N+ patients could be therefore attributed to expression of CXCR4, uPAR and VIM (and possibly SNAIL)." (PMID 24709997, 2014). "The CXCL12/CXCR4 loop may stimulate tumor cell proliferation and induce extracellular matrix rearrangement, necessary for metastasis formation." (PMID 24944647, 2014).
tumor (continued). "The CXCR4 gene can further be transactivated by the activation of hypoxia-inducible factor- (HIF-) 1α, arising either from loss of the von-Hippel-Lindau tumor suppressor (VHL) or due to the hypoxic conditions observed frequently in tumor tissues." (PMID 24966464, 2014). "In addition, emodin treatment significantly suppressed metastasis to the lungs in an orthotopic HCC mice model and CXCR4 expression in tumor tissues." (PMID 23472074, 2013). "CXCR4 activation has been linked to ERK1/2, Akt, and FAK phosphorylation, which are important pathways regulating the survival, proliferation and invasion of tumor cells." (PMID 23865743, 2013). "It is well known that CXCR4 is highly expressed in malignant PCa cells and is involved in metastasis; however, few reports have observed a subcellular localization for CXCR4 other than the PM and endosomes in tumor tissues." (PMID 23468933, 2013). "Here, we propose that the cure rates for this malignancy might be improved by targeting MMP-2-mediated SDF-1/CXCR4 expression and pathway, thereby preventing reconstitution of tumor vasculature following radiation." (PMID 23381805, 2013). "The hybrid nature of the CXCR4 targeting imaging agent MSAP-Ac-TZ14011 has allowed us to successfully demonstrate the concept of integrating target selection in fresh (biopsy) tumor tissue with in vivo imaging and ex vivo microscopic validation, all using a single imaging agent." (PMID 23326303, 2013). "Since CXCR7 is the other known receptor for SDF-1 α, the question must be raised whether CXCR7 has a similar function as CXCR4 in the tumor cell biology of EC." (PMID 24074251, 2013). "This theory may hold true for tumor cells that express CXCR4 at the nucleus, and secrete SDF1α from the same cell." (PMID 23468933, 2013). "Interestingly, the MIF and CXCR4 expression levels in tumor cells and in TILs were positively correlated, and the combined expression of MIF and CXCR4 in tumor cells was an adverse independent factor for survivals of ESCC patients." (PMID 23497377, 2013). "Furthermore, emodin treatment led to the downregulation of migration and invasion induced by the ligand CXCL12 metastasis to the lungs in an orthotopic HCC mice model and CXCR4 expression in tumor tissues." (PMID 23472074, 2013). "However, the expression pattern of MIF and CXCR4 proteins in tumor microenvironments and their impact on the survival of cancer patients are still unclear." (PMID 23497377, 2013). "In OS, CXCL12 interacting with CXCR4 was shown to drive tumor progression and metastasis." (PMID 24040160, 2013). "Furthermore, the expression of MIF and CXCR4 in tumor cells were independent factors for reduced DFS and OS in metastatic/recurrent ESCC patients (P < 0.05)." (PMID 23497377, 2013). "Tumor cells expressing CXCR4 metastasize to target organs that express high levels of CXCL12." (PMID 23902739, 2013). "Furthermore, the expression levels of MIF and CXCR4 in tumor cells were independent predictive factors for survivals in patients with metastatic/recurrent ESCC." (PMID 23497377, 2013). "Our data revealed that CXCR4 could be expressed in the nucleus, cytoplasm and cell membrane of tumor cells and TILs." (PMID 23497377, 2013). "Ac-TZ14011 was shown to bind selectively to CXCR4 and could be used to visualize CXCR4 positive tumor lesions in vivo." (PMID 23326303, 2013). "Therefore, the protein levels of MIF and CXCR4 in diverse cell populations within the tumor microenvironment have different clinically prognostic values in ESCC." (PMID 23497377, 2013). "Prostaglandin E2 can induce CXCR4 expression in the myeloid derived suppressor cells (MSDCs), which may be subsequently recruited into the tumor by CXCL12 present in the ascitic fluid." (PMID 24384839, 2013).
tumor (continued). "It further supports that IL-19 not only directly facilitates cell proliferation, cell migration, and metastasis but it also prompts the expression of IL-1β, IL-6, TGF-β, MMP-2, MMP9, CXCR4, and fibronectin, which supply of a microenvironment for tumor growth and metastasis." (PMID 23710200, 2013). "Furthermore, using animal tumor models, encouraging results from our group and others have indicated that CXCR4 antagonists have in vivo anti-cancer activity as well." (PMID 23484027, 2013). "CXCR4 expression has been reported in at least 23 epithelial, mesenchymal and hematopoietic cancers, indicating the importance of this ligand/receptor axis in tumor aggressiveness and metastasis." (PMID 24137439, 2013). "Therefore, we evaluated the expression of MIF and its receptor CXCR4 protein in tumor cells and TILs of tumor microenvironment in 136 resected ESCC specimens using immunohistochmeistry staining." (PMID 23497377, 2013). "The advantage of the CXCR4-β-arrestin 2 reporter is that this system quantifies activation of CXCR4 in ovarian cancer cells by all sources of CXCL12 in the tumor microenvironment, while our previous assay detected only CXCL12 engineered with a fusion protein for complementation imaging." (PMID 23372646, 2013). "The SDF-1α-CXCR4 interaction promotes tumor progression by several possible mechanisms." (PMID 23484027, 2013). "Furthermore, inhibition of CXCR4-signaling by AMD3100 during pre-treatment of tumor cells with wound fluid abolished the effect of wound fluid on tumor growth." (PMID 23593347, 2013). "Furthermore, the combined expression of MIF and CXCR4 in tumor cells was an independent predictive factor for DFS and OS according to the multivariate Cox model analysis." (PMID 23497377, 2013). "Accordingly, the suppression of tumor growth in treated mice may be explained by the inhibition of CXCR4+ tumor cell proliferation and the diminishing recruitment of CXCR4+ angiogenic cells." (PMID 24137439, 2013). "CXCR4 expression of the tumor specimen was determined by immunohistochemistry." (PMID 24376734, 2013). "Binding of the CXCL12 chemokine to its receptor (CXCR4) may regulate tumor dissemination in prostate tumor cells by enhancing expression of αvβ3 integrins." (PMID 24490159, 2013). "Similar to the in vitro evaluation of fluorescently labeled imaging agents, flow cytometriy could be used to analyze the level of CXCR4 expression in the tumor cell suspensions." (PMID 23326303, 2013). "Direct, ex vivo, incubation of the tumor tissue will probably enable visualization of “all” CXCR4 positive cells present, systemic administration will most certainly only stain cells that could be reached by the tracer via the vascular network." (PMID 23326303, 2013). "Interestingly, the chemokine, CXCL12 (SDF-1), and its receptor, CXCR4, played an essential role in development of tumors in this model, as blockade of these molecules abrogated tumor growth." (PMID 23936541, 2013). "It is possible that the increase in CXCR4 gene expression may be due to the recruitment of other immune cells and hematopoietic progenitor cells into the tumor microenvironment, but the biological significance in this context remains unknown." (PMID 24312199, 2013). "MIF and CXCR4 levels were measured by immunochemistry in tumor specimens from 136 resected ESCC." (PMID 23497377, 2013). "Moreover, we have previously documented that murine bone marrow-derived CXCR4-positive progenitor cells contribute to tumor growth by promoting tumor angiogenesis." (PMID 24040017, 2013). "PAX3-and PAX7-FKHR gene fusion, mutations in the von Hippel Lindau gene, hypoxic conditions in the tumor microenvironment, NF-κB, vascular endothelial growth factor, and tumor necrosis factor alpha have all been found to regulate CXCR4 overexpression in different tumor cells." (PMID 23472074, 2013).